MUTYH (mutY DNA glycosylase)
Diseases named in the same sentence as MUTYH in open-access papers (continued):
Sharing a sentence is not in itself a finding about the gene and the disease.
Familial adenomatous polyposis (65 papers, 2008 to 2025). Familial adenomatous polyposis (FAP) is characterized by the development of hundreds to thousands of adenomas in the rectum and colon during the second decade of life. "A series of clinical observations have shown that biallelic and heterozygous germline pathogenic variants in MUTYH are associated with the development of familial adenomatous polyposis." (PMID 39684352, 2024). "As expected, MUTYH associated with recessive familial adenomatous polyposis, the only two homozygotes of which also carry biallelic MUTYH variants, had the highest allele frequency, followed by VHL, BRCA1, BRCA2, and PALB2." (PMID 39301547, 2024). "PVs/LPVs in MUTYH are associated with colorectal adenomatous polyposis autosomal recessive, while recent literature data revealed the association between monoallelic MUTYH variants and several type of cancer." (PMID 37065479, 2023). "A series of clinical observations have shown that biallelic and heterozygous germline pathogenic variants in MUTYH are probably associated with the development of familial adenomatous polyposis." (PMID 38201513, 2023). "The mutations on the MUTYH gene have been associated with the autosomal recessive form of the syndrome of familial adenomatous polyposis (MYH associated polyposis)." (PMID 31207142, 2019). "Familial adenomatous polyposis is most frequently caused by pathogenic variants in either the APC gene or the MUTYH gene." (PMID 25604157, 2015). "Biallelic germ-line mutations in human MUTYH have been identified in patients affected by colorectal adenomatous polyposis." (PMID 20706593, 2010). "In addition to FAP and MUTYH-associated polyposis, colorectal adenomatous polyposis can be caused by other hereditary diseases, including polymerase proofreading-associated polyposis, NTLH1 tumor syndrome, and MBD4-associated neoplasia syndrome." (PMID 38647838, 2024). "This group includes familial adenomatous polyposis, attenuated familial adenomatous polyposis, MUTYH-associated polyposis, NTHL1-associated polyposis, Peutz–Jeghers syndrome, juvenile polyposis syndrome, Cowden syndrome, Lynch syndrome, and Muir–Torre syndrome." (PMID 36553592, 2022). "Similarly, MUTYH germline mutations cause an autosomal recessive form of familial adenomatous polyposis known as MYH-associated polyposis (MAP)." (PMID 36531003, 2022). "Monoallelic pathogenic variants in genes associated with autosomal recessive conditions, including MUTYH-associated polyposis (familial adenomatous polyposis-2, FAP2; MIM: 608456) and Fanconi anaemia, complementation group I (FA; MIM: 609053), accounted for the remaining 10.0%." (PMID 29736259, 2018). "Furthermore, this type of cancer often occurs in individuals with genetic diseases such as Peutz–Jeghers syndrome, familial adenomatous polyposis, Lynch syndrome, Cowden syndrome, juvenile polyposis, Li–Fraumeni syndrome, and MUTYH-associated adenomatous polyposis." (PMID 40332338, 2025). "A small proportion of CIN tumors are inherited and arise secondary to germline mutations in the APC gene as seen in familial adenomatous polyposis (FAP) or the MUTYH gene (as seen in MUTYH-associated polyposis)." (PMID 32231042, 2020). "APC and MUTYH genes are mutated in 70–90% and 10–30% of familial adenomatous polyposis cases (FAP) respectively." (PMID 29954149, 2018). "Familial Adenomatous Polyposis (FAP) is caused by pathogenic variants in APC or MUTYH (MAP)." (PMID 39859530, 2025). "We also analyzed another inheritable precancerous condition of CRC, familial adenomatous polyposis (FAP) and MAP (MUTYH‐Associated Polyposis)." (PMID 39554798, 2024). "The most common cause of colorectal adenomatous polyposis is hereditary adenomatous polyposis, typically resulting from germline pathogenic variants in the APC or MUTYH genes." (PMID 38647838, 2024).
Familial adenomatous polyposis (continued). "Some of these were associated with AR cancer, such as MUTYH (MIM: 604933), a well-known DNA repair gene in which mutation causes an AR form of familial adenomatous polyposis (MIM: 132600)." (PMID 31589614, 2019). "Familial adenomatous polyposis (FAP) is caused by inactivating mutations in APC and MUTYH, and it is considered a risk factor for hereditary PDAC." (PMID 30134550, 2018). "First, we searched for deleterious variants in the genes associated with adenomatous polyposis of the colon (APC, MUTYH, NTHL1, POLD1, and POLE)." (PMID 27217144, 2016). "In addition, there is an increased risk for colorectal cancer associated with mutations in the APC (familial adenomatous polyposis [FAP] or attenuated-FAP) and MUTYH (MUTYH-associated polyposis) genes." (PMID 25204323, 2014). "Scientific interest around MUTYH grew dramatically when it emerged that mutations in such gene were present in patients diagnosed with AFAP (Attenuated Familial Adenomatous Polyposis) without mutations in the APC gene." (PMID 41001951, 2025). "These include APC for familial adenomatous polyposis (FAP); BMPR1A and SMAD4 for Juvenile Polyposis Syndrome (JPS); MUTYH for MUTYH-associated polyposis; PTEN for PTEN tumor/hamartoma syndrome (or Cowden syndrome/Bannayan–Riley–Ruvalcaba syndrome); and STK11 for Peutz–Jeghers syndrome." (PMID 37965459, 2023). "The tumor may be sporadic or associated with inherited conditions such as familial adenomatous polyposis (FAP) and mutY DNA glycosylase (MUTYH)-associated polyposis (MAP)." (PMID 31803624, 2019). "These include familial adenomatous polyposis (FAP), Gardner syndrome, Lynch syndrome (HNPCC), Cowden syndrome, Turcot syndrome, juvenile polyposis syndrome, Peutz–Jeghers syndrome, and MUTYH-associated polyposis." (PMID 40733666, 2025). "Certainly, APC and MUTYH are not the only genes predisposing to the familial polyposis." (PMID 29954149, 2018). "As expected, there was significantly more CRC in the EOCRC group with cancers related to familial adenomatous polyposis (FAP), Lynch syndrome, or MUTYH than LOCRC (18/406 vs. 27/6608, p < 0.001)." (PMID 40563564, 2025). "Among these, there are familial adenomatous polyposis (FAP), hereditary non-polyposis colorectal cancer (Lynch syndrome), polyposis associated with MUTYH gene mutations, Gardner syndrome, Turcot syndrome, juvenile polyposis syndrome, Peutz–Jeghers syndrome, and Cowden syndrome." (PMID 37763765, 2023). "Another major factor is genetic predisposition, as 10% of the processes are related to hereditary CRC syndromes such as MUTYH gene-associated polyposis (MAP), familial adenomatous polyposis (FAP) or hereditary non-polyposis-associated CRC (Lynch syndrome) and the family history of CRC." (PMID 38455079, 2023).
breast cancer (57 papers, 2009 to 2025). A primary or metastatic malignant neoplasm involving the breast. "In MUTYH gene, a deleterious missense variant (c.1187G>A; p.Gly396Asp) was detected in a breast cancer patients with a strong family history of breast cancer." (PMID 37656691, 2023). "Lastly, MUTYH mutations that are known to predispose to recessively inherited colorectal polyposis and cancer have also been associated with breast cancer susceptibility, although there are some contradictory findings published." (PMID 36011273, 2022). "This variant is the most frequent of all MUTYH mutations in various populations, but the association between this variant and breast cancer remains controversial." (PMID 33827469, 2021). "Monoallelic MUTYH variants have been reported in families with both colorectal and breast cancer and there is some evidence on increased breast cancer risk in women with monoallelic variants." (PMID 30564557, 2018). "Fourth, an increased frequency of mammary tumors was found in both MUTYH- and APC-deficient mice compared to mice with an APC deficiency only." (PMID 22297469, 2012). "Indeed, some authors detected LOH of MUTYH due to copy number loss in the tumor of two breast cancer patients who had a first germline MUTYH pathogenetic variant." (PMID 38790183, 2024). "We aimed to assess if MUTYH mutations contribute to breast cancer susceptibility." (PMID 38254803, 2024). "Nevertheless, further studies are required to confirm the association between MUTYH-monoallelic variants and risk of breast cancer, which can provide additional knowledge for assessing the patient’s risk and the potential of developing a new therapeutic target." (PMID 37656691, 2023). "Also identified were two pathogenic MUTYH variants, previously associated with colon cancer but increasingly implicated in breast cancer." (PMID 38028594, 2023). "Monoallelic variants in MUTYH gene may act as low-penetrance breast cancer risk and could contribute to breast cancer development in synergy with additional risk factors such as age, ethnicity, or even environmental and lifestyle factors." (PMID 37656691, 2023). "Several diseases, including breast cancer, diabetes, MUTYH-Associated Polyposis, Late-Onset Alzheimer’s Disease, Parkinson’s Disease, lung and liver disease, Chronic Kidney Disease, Familial Hypercholesterolemia, anemia, nerve and heart damage, and iron overload." (PMID 37273966, 2022). "The first exception was a woman with breast cancer with a heterozygous pathogenic variant in MUTYH." (PMID 35190596, 2022). "A study focused on MUTYH-associated extracolonic cancers demonstrated that monoallelic variants are associated with an increased risk of gastric and liver cancers, as well as a slightly increased risk of endometrial and breast cancers." (PMID 34026625, 2021). "Of these, genes hypothesized to have a tumor-suppressor function included LINC00886, MAN2C1, SNUPN, and STC1, while YBEY, SEMA4A, and MUTYH may have an oncogenic role in breast carcinogenesis based on their associations with breast cancer risk." (PMID 32139696, 2020). "In this context, one could mention that heterozygous variant p.(Gly396Asp) in the MutY DNA glycosylase gene has been shown to be associated with an elevated risk of breast cancer also in a study on 930 Sephardi Jewish women of North African origin." (PMID 28634180, 2017). "Therefore, we aimed to assess if MUTYH mutations contribute to breast cancer susceptibility." (PMID 38254803, 2024). "Furthermore, certain pathogenic variants of MUTYH, especially the p.Tyr179Cys variant, may contribute to an overall increased risk of developing breast cancer in males [odds ratio (OR): 4.54; 95% confidence interval (CI): 1.17 - 17.58; p = 0.028]." (PMID 39233942, 2024). "There has been controversy about whether MUTYH mutations are associated with breast cancer." (PMID 38254803, 2024). "Also, the occurrence of MUTYH mutations in patients with breast cancer has been examined." (PMID 25937855, 2014).
breast cancer (continued). "The results of our study indicate that the prevalence of germline alterations in MUTYH in our series is 1.6%, and among breast cancer patients, it is 1.8%." (PMID 38254803, 2024). "The most frequent variants for breast cancer were in BRCA1 (deletion (ex 9–12) and c.115T > A (p.Cys39Ser)) and MUTYH c.118G > A (p.Gly396Asp); these variants were found in four patients each." (PMID 36833268, 2023). "Pathogenic variants were identified in CHEK2, MUTYH, and RAD51B in four breast cancer patients, which represented 8.3% of the cohort." (PMID 31780696, 2019). "However, a correlation between MUTYH variants and breast cancer remains unclear." (PMID 29093764, 2017). "Homozygosity or double heterozygosity (DH) for pathogenic variants (PVs) in MUTYH causes MAP, but several studies suggest that monoallelic PVs may also increase cancer risk, mainly CRC and breast cancer (BC)." (PMID 41001951, 2025). "Studies suggest a slight link between breast cancer and monoallelic MUTYH mutations in Sephardi Jewish and Chinese women, but no significant risk was found in Canadian and Dutch cohorts." (PMID 39390525, 2024). "It was not possible to detect an association between MUTYH mutations and breast cancer, obtaining a non-significant OR." (PMID 38254803, 2024). "The diagnostic process of women affected by breast cancer on a hereditary basis involves a first-level analysis of BRCA1 and BRCA2 genes and, if negative and clinically indicated, a second-level analysis of other cancer genes, including MUTYH." (PMID 38790183, 2024). "Some studies demonstrate an increased risk of breast cancer in patients with pathogenic mutations in MUTYH, but large international clinical trials have not yet been conducted." (PMID 38201513, 2023). "Here, MUTYH c.1187G > A was reported in two unrelated individuals with breast cancer." (PMID 33827469, 2021). "Meanwhile, MUTYH heterozygous or homozygous mutations among breast cancer patients with or without a history of the disease evidenced an association of MUTYH with an increased risk of BC22." (PMID 33558524, 2021). "In this study, the remaining pathogenic variants in breast cancer occurred in CDH1 and MUTYH." (PMID 33827469, 2021). "However, our findings did not reveal a substantial association between MUTYH mutations and breast cancer." (PMID 38254803, 2024). "However, more than 10% of a European cohort appeared to be related to pathogenic germline variants in DNA damage repair (DDR) genes MUTYH, CHEK2, and BRCA2, the first known to be correlated to MYH-associated polyposis and the others to a higher risk for breast cancer." (PMID 34638668, 2021). "Some of these studies found a significant increase in MUTYH mutations in breast cancer patients, while others could not find this potential association." (PMID 25937855, 2014). "In recent studies, MUTYH-monoallelic germline variants have been reported in patients with early-onset or familial breast cancer and in BRCA1/2 negative breast cancer patients." (PMID 37656691, 2023). "While a study of over 30,000 women with breast cancer found no significant increase in risk of breast cancer in women with MUTYH, a recent study of 165 women with BRCA1/2-negative IBC found that MUTYH was the most commonly mutated gene (3.6%)." (PMID 36091166, 2022). "Among the individuals with pathogenic variants, 50% were diagnosed with breast cancer and had mutations in BRCA1, CDH1 and MUTYH – gene not typically associated with this cancer." (PMID 33827469, 2021).
breast cancer (continued). "A more detailed analysis did note higher response rates for patients with DDR+ breast cancer (55% vs 25% DDR-), BRCA1 mutations (50% vs 23% DDR-), and MUTYH mutations (40% vs 23% DDR-), but none of these subgroups reached statistical significance due to the small sample sizes." (PMID 38348036, 2024). "Our larger study supports this finding and found significant differences in the prevalence of some breast cancer genes (BRCA1, MSH6, and MUTYH) between the two ethnic groups, suggesting that germline genetics may impact ethnic differences in breast cancer tumor characteristics and survival." (PMID 34857041, 2021). "Furthermore, variants in other cancer susceptibility genes (i.e., MUTYH and CDKN2A) are sometimes reported through breast cancer risk assessment, but were not assessed in this study." (PMID 32866190, 2020). "We carried out a hospital-based case-control study in a Caucasian Portuguese population (287 cases and 547 controls) to estimate the susceptibility to non-familial breast cancer associated with some polymorphisms in mismatch repair genes (MSH3, MSH4, MSH6, MLH1, MLH3, PMS1 and MUTYH)." (PMID 19781088, 2009).
Lynch syndrome (57 papers, 2009 to 2026). An autosomal dominant hereditary neoplastic syndrome characterized by the development of colorectal carcinoma and a high risk of developing endometrial carcinoma, gastric carcinoma, ovarian carcinoma, renal pelvis carcinoma, and small intestinal carcinoma. "A pathogenic germline mutation in MUTYH, involved in Lynch syndrome and encoding a DNA base excision repair enzyme, was reported in a pediatric case of spinal cord DMG/K27M." (PMID 32680567, 2020). "Digenic inheritance of monoallelic MSH6 and MUTYH variants has been suggested to predispose to Lynch syndrome‐associated cancers." (PMID 32615015, 2020). "Our results demonstrated that patients with Lynch syndrome harboring at least one risky genotype in MUTYH, NUDT1, and ERCC2 SNPs were at an increased risk of CRC compared to those without risky genotype." (PMID 29664240, 2018). "Our findings revealed that polymorphisms of DNA repair genes that include NUDT1,ERCC2, and MUTYH are associated with CRC in patients with Lynch syndrome in Chinese population." (PMID 29664240, 2018). "Biallelic mutations in MUTYH have been shown to mimic Lynch syndrome by disrupting base excision repair and resulting in a somatic loss of function of mismatch repair." (PMID 28591191, 2017). "Similarly to studies on Western populations, mutations in genes other than those associated with the Lynch syndrome, including MUTYH, BRCA2, ATM, BRIP1, CDKN2A, and NF1, were identified." (PMID 39061183, 2024). "In our study, 8 patients were identified with pathogenic or likely pathogenic germline mutations in non-Lynch syndrome genes (MUTYH, GALNT 12, POLE, MPL, ATM, and ERCC4), which indicated that there may be other genes outside of Lynch syndrome associated with endometrial cancer." (PMID 30886832, 2019). "Multiple case reports have identified MTS patients with tumors that show MSS and biallelic inactivation of MUTYH, and their authors suggest MAP as an alternative etiology for MTS, separate from a variant of Lynch syndrome." (PMID 40002254, 2025). "The genes with the highest prevalence of P/PV variants included CHEK2 (26%), MUTYH (21%), BRCA2 (8%), APC I1370K (8%), and Lynch Syndrome-associated (7%)." (PMID 40770526, 2025). "Out of 103 patients who underwent germline testing for Lynch syndrome, 19 (18.4%) showed a mutation in MMR genes with pathogenic or likely pathogenic significance and 8 (7.8%) in other CRC-associated genes (APC, CHEK2, MUTYH)." (PMID 39457591, 2024). "In our patient population meeting genetic test criteria for HBOC or Lynch syndrome, 12.5% of patients were found to have a pathogenic mutation, with the most common being in BRCA1/2 followed by MUTYH and CHEK2." (PMID 38136308, 2023). "If a single-gene approach to testing was utilized in this scenario, practitioners would have likely started with the APC or MUTYH gene based on his adenoma history and then moved on to the mismatch repair genes of Lynch syndrome." (PMID 29225998, 2016). "It is well established that early screening for polyps in family members of patients with characterized mutations in MMR (Lynch syndrome), APC (FAP), or MUTYH (MAP) genes is beneficial in improving detection of malignant changes and reduces mortality." (PMID 24550697, 2014). "In a Europe-based study, MUTYH accounted for only 3.6% of Lynch syndrome–like cases." (PMID 38136308, 2023).